DLC1 (DLC1 Rho GTPase activating protein)
Diseases named in the same sentence as DLC1 in open-access papers (continued):
Sharing a sentence is not in itself a finding about the gene and the disease.
non-small cell lung carcinoma (18 papers, 2008 to 2024). A group of at least three distinct histological types of lung cancer, including non-small cell squamous cell carcinoma, adenocarcinoma, and large cell carcinoma. "Transfection of DLC1 in vitro caused decreased proliferation and colony forming potential of non-small cell lung carcinoma (NSCLC) cells and breast carcinoma cells." (PMID 19912643, 2009). "Previously, FBXW5 was proposed to form a complex with CUL4A in non-small cell lung cancer, which led to the degradation of the tumor suppressor protein, DLC1, a Rho GTPase-activating protein, ultimately promoting cell proliferation." (PMID 35210431, 2022). "Caveolin-1, the main component of caveolae, forms a functional complex with DLC1 in non-small cell lung cancer cells by interacting with a region whose binding is reduced by deletion of aminoacids 929 to 957 in DLC1-START." (PMID 34727930, 2021). "In H1299 cells miR-200c targets multiple non-small cell lung cancer prognostic markers DLC1, ATRX, and HFE." (PMID 24997798, 2014). "In metastatic non-small-cell lung cancer cells (NSCLC), PPARγ overexpression has been shown to inhibit cell invasion and to be associated with DLC1 induction." (PMID 24265769, 2013). "In addition, a GAP-dead DLC1 mutant in a non-small cell lung cancer cell line can still partially inhibit anchorage-independent growth, and an inactive form of DLC1 in NIH3T3 fibroblasts can partially inhibit cell migration." (PMID 34727930, 2021). "DLC-1 tumor suppressor inhibited TGF-β1 signaling and regulated CD105 expression in human non-small cell lung carcinoma cells." (PMID 33425911, 2020).
colorectal cancer (17 papers, 2013 to 2024). A primary or metastatic malignant neoplasm that affects the colon or rectum. "Increasingly research has shown that DLC1 is linked with the development and progression of numerous malignancies such as ovarian, breast, and colorectal cancers, and is involved in suppressing metastasis." (PMID 37737712, 2023). "Second, we determined the TCGA colorectal cancer database contains several cancer-associated DLC1 point mutants whose mutations lie in the START domain and analyzed 7 of them." (PMID 34727930, 2021). "In addition, we have identified several colorectal cancer-associated DLC1-START mutants that are deficient for all or some of these interactions and possess reduced tumor suppressor function but intact RhoGAP activity." (PMID 34727930, 2021). "We identified three classes of DLC1 START domain mutants among the seven TCGA colorectal cancer mutants analyzed." (PMID 34727930, 2021). "We selected 7 missense mutations from TCGA colorectal cancer and created isogenic stable clones of the different GFP-tagged mutant DLC1 proteins in H358 cells." (PMID 34727930, 2021). "miR‐106b promoted colorectal cancer cell migration and invasion by directly targeting DLC1 20.miR‐106a also has been reported to play an oncogenic role in pancreatic cancer." (PMID 27230463, 2016). "DLC-1 expression was decreased in colorectal cancer tissues and diminished through transient transfection with miR-483-3p." (PMID 27366946, 2016). "The regulation of DLC-1 by miR-141 has also been shown in colorectal cancer." (PMID 32316405, 2020). "In addition to miR-141 inversely correlating with DLC1, the transient or stable expression of miR-141 in Lovo colorectal cancer cells promoted cell growth, migration and invasion, as well as tumor growth." (PMID 32353968, 2020). "Second, except for colorectal cancer, DLC1 is down-regulated to a greater degree in the tumors, in terms of both the magnitude of the reduction and the fold-reduction compared with DLC1 expression in the respective normal tissue, than the other two family members." (PMID 27174913, 2016). "By targeting hepatoma 1 (DLC-1), exosomal miR-106b-3p induced EMT in colorectal cancer, thereby promoting lung metastasis of colorectal cancer cells." (PMID 37046819, 2023). "Re-expression of DLC1 upon DZNep treatment was also observed in different cancer cell lines including the nasopharyngeal carcinoma cell line CNE2, colorectal carcinoma cell line HCT116 and cervical adenocarcinoma cell line HeLa." (PMID 23826380, 2013). "DLC1 is negatively regulated by miRNAs in colorectal cancer, however, the possible DLC1 regulation by miR-26a has not been evaluated." (PMID 27517917, 2016). "By comparing the DLC-1 protein levels in 10 primary tumor biopsies to its adjacent non-cancerous tissues using Western blot, we found DLC-1 levels in colorectal cancer tissues to be much lower than the adjacent normal tissues." (PMID 27366946, 2016). "However, the pathogenicity of DLC-1 epigenetic silencing in the mucosa-adenoma-carcinoma transformation process of colorectal cancer (CRC) has not been studied." (PMID 23509688, 2013). "DLC-1 is a Rho GTPase-activating protein (RhoGAP), could facilitate melanoma cell invasion and metastasis by cooperating transcription factor FOXK1 to promote MMP9 expression and enhancing colorectal cancer metastasis by the epithelial-to-mesenchymal transition." (PMID 33682883, 2021).
colon carcinoma (13 papers, 2012 to 2024). "DLC1 has most frequently been linking to colon cancer, but work in mouse models has shown that it is a critical gene for brain development during embryogenesis." (PMID 32596987, 2020). "DLC-1 has been known as tumor suppressor gene in many kinds of cancers including liver, lung, breast, brain, prostate and colon cancers." (PMID 26846339, 2016). "It was reported that DLC1 inhibited the growth and invasion of colon cancer cells through the Wnt/β-catenin signaling pathway by upregulating GSK-3β, and downregulating β-catenin." (PMID 26223867, 2015). "Reactivation of DLC1 results in suppression of tumor cell proliferation and reduces tumorigenicity in liver and colon cancer." (PMID 25425654, 2014). "Studies of lung and colon cancer show that underexpression of DLC1 frequently co-occurs with deregulated expression of cell cycle genes such as CDK6, CDK4, CDKN2A, and CDKN2B." (PMID 25425654, 2014). "We determined the mRNA expression of DLC-1 gene in 4 colon cancer cell lines, normal mucosa, adenomas, and CRC tissues." (PMID 23509688, 2013). "MS-HRMA was designed to examine the methylation status in promoter regions of DLC-1 in four colon cancer cell lines and various tumor and adjacent normal tissues." (PMID 23509688, 2013). "A previous study showed that miR-186-5p was abundant in M2 macrophage-derived EVs, and M2 macrophages-derived EVs delivered miR-186-5p to cells by targeting DLC1 expression, thereby enhancing the growth and motility of colon cancer cells by activating the β-catenin pathway." (PMID 37400770, 2023). "Low DLC1 expression is found to frequently co-occur with aberrant expression of cell cycle genes including CDK6 in human lung and colon cancer." (PMID 25425654, 2014). "Moreover, overexpression of p120RasGAP in colon carcinoma cells that harbored mutant Ras and thus were resistant to the negative regulation of Ras by p120RasGAP, increased the level of endogenous active Rho in a DLC1-dependent manner and antagonized the growth-suppressive effects of DLC1." (PMID 22580498, 2012). "A recent study reported that low DLC1 by itself did not have prognosis value in colon cancer patients, but there is a prognostic significance when low DLC1 was combined with low p15 or high Cdk6 in colon cancer patients." (PMID 26223867, 2015).
gastric cancer (11 papers, 2013 to 2023). A primary or metastatic malignant neoplasm involving the stomach. "Further, DLC1-negative gastric cancer patients exhibit shorter survival rates and higher recurrence risks, thereby indicating that a low expression of the DLC1 gene is associated with gastric cancer." (PMID 36984515, 2023). "The highly dysregulated gene predicted in gastric cancer is DLC1, having more than an 8-fold change in its expression (p-value ≤ 0.0001) and being a down-regulated gene, and a low expression of DLC1 is associated with gastric cancer." (PMID 36984515, 2023). "DLC1-negative gastric cancer patients exhibit shorter survival rates and higher recurrence risks, thereby indicating that a low expression of the DLC1 gene is associated with gastric cancer." (PMID 36984515, 2023). "In one of the studies carried out by YuqiSu and collaborators, DLC1 was identified to be significantly lower in the gastric cancer samples, mainly in tumors of higher disease stages, with increased invasion, distant metastasis, and lymph node metastasis." (PMID 36984515, 2023). "A differential expression analysis of autophagy-related genes (ARGs) in gastric cancer was carried out by Li and collaborators, who report a total of seven prognosis-related ARGs, including DLC1, as independent prognostic markers for gastric cancer." (PMID 36984515, 2023). "This indicates that DLC1 can be used as a potential druggable target for specific subsets of gastric cancer." (PMID 36984515, 2023). "The expression of DLC1 has been reported to be reduced in gastric cancer, but the sample size in these studies was small." (PMID 36173625, 2022). "Expression of DLC1 is silenced in human gastric cancer, prostate cancer, multiple myeloma and leukemia cell lines." (PMID 30278072, 2018). "DLC1 expression can be induced by histone deacetylase inhibitors in prostate and gastric cancer cells." (PMID 28903430, 2017). "Further validation of DLC1 and other significant DEGs identified can be conducted, which can provide new research directions for the detection and treatment of cancer and, at the same time, improve the prognosis of gastric cancer using these biomarkers." (PMID 36984515, 2023). "Furthermore, the suppression of tumor growth using an inhibitor of the RHOA downstream effector, ROCK, suggests DLC1 as a druggable target for gastric cancer." (PMID 36984515, 2023). "The expression of DLC1 was identified to be significantly lower in the gastric cancer samples." (PMID 36984515, 2023). "Hence, apart from several other genes, we report DLC1 as a key regulator that can act as a potential biomarker for the diagnosis and therapeutics of gastric carcinoma." (PMID 36984515, 2023). "Histone deacetylase inhibitor activates DLC1 promoter in prostate and gastric cancer cells." (PMID 28903430, 2017). "In gastric cancer, a large number of genes (e.g., CDKN2A, CDK2AP2, CDH1, MGMT, RASSF1, RUNX3, and DLC1) have been shown to be suppressed by CpG island hypermethylation." (PMID 23179365, 2013). "The methylation study suggests that five out of the seven DLC1 non-expressing gastric cancer cell lines were methylated in the DLC1 CpG island, which is not uncommon in gastric cancer." (PMID 36984515, 2023).
ovarian carcinoma (11 papers, 2008 to 2024). A malignant neoplasm originating from the surface ovarian epithelium. "A meta-analysis study involving 1815 cancer cases demonstrating a low expression of DLC-1 was associated with advanced stages of cancer, including ovarian cancer." (PMID 32316405, 2020). "The loss of DLC-1 was not only limited to liver cancer as it has also proven to be frequently loss in multiple cancers such as breast, colon and ovarian cancer." (PMID 26260454, 2015). "An inverse relation between EZH2 and DLC1 expression was observed in the liver, lung, breast, prostate, and ovarian cancer tissues." (PMID 23826380, 2013). "Using gene transfection technology, DLC-1 gene high expression can inhibit the ovarian cancer cell line OVCAR-3 cells proliferation significantly." (PMID 23988121, 2013). "Moreover, low expression of DLC1 with high expression of pFAK Y397 (phosphorylated FAK) was detected in advanced ovarian cancers." (PMID 28881822, 2017). "The expression of DLC1 was significantly associated with advanced FIGO stage, ascites, and positive lymph node metastasis, which suggested that DLC1 might be involved in the invasion and metastasis of ovarian cancer." (PMID 23988121, 2013). "However, multivariate Cox analysis showed that only histological differentiation (HR = 2.467, 95% CI: 1.126–5.407) and DLC1 combined with p-FAK Y397 expression (HR = 3.922, 95% CI: 1.126–13.664) were independent risk factors that influenced the prognosis of advanced stage epithelial ovarian cancer." (PMID 22272086, 2011). "The gene DLC-1 is a tumor suppressor, and ZEB2 is a transcriptional repressor, which have been shown to be downregulated in ovarian cancers compared to normal tissues." (PMID 32316405, 2020). "In next steps, the potential signaling pathways that regulate DLC1 and PAI-1 expression in ovarian cancer cell migration and invasion will be discussed." (PMID 23988121, 2013). "Expression of DLC1 has a negative correlation with expression of pFAK Y397 in advanced ovarian cancer." (PMID 28881822, 2017). "Ovarian cancer patients with negative expression of DLC1 and positive expression of PAI-1 had the worst overall survival time compared to other patients." (PMID 23988121, 2013). "From a meta-analysis study, it was shown that DLC1 expression was downregulated in the advanced stages compared to the early-stage cancer in 19 eligible studies, including epithelial ovarian cancer (EOC), but those studies did not mention the histological subtypes of EOC." (PMID 34071861, 2021). "Furthermore, our results focused on methylation status of CAMs and revealed a 3-gene (CTNNA1, DLC1, MFAP4) methylation signature with a prognostic significance that may provide a new biomarker for personalized treatment in ovarian cancer." (PMID 28881822, 2017). "Furthermore, Kaplan-Meier survival curves demonstrated that ovarian cancer patients with negative expression of DLC1 and positive expression of PAI-1 had the worst overall survival time compared to other patients." (PMID 23988121, 2013).
prostate carcinoma (10 papers, 2009 to 2026). A carcinoma that arises from epithelial cells of the prostate gland. "Further studies showed that hypermethylation of DLC1 gene promoter is responsible for the loss of its function as a tumor suppressor in a subset of liver, colon and prostate cancers." (PMID 24627003, 2014). "DLC1 is frequently down regulated in prostate cancer by either epigenetic modifications or deletion and its genomic under-representation at chromosome 8p is associated with aggressive form of prostate cancer." (PMID 24683532, 2014). "DLC1 regulates E-cadherin and suppresses highly metastatic prostate cancer cell invasion by modulating the Rho pathway." (PMID 41516419, 2026). "This is in contrast to the methylation pattern identified in DLC1 in human prostate cancer in which the Sp1 sites are more heavily methylated, contributing to silencing." (PMID 19912643, 2009). "DLC1 was expressed in many normal tissues, but its expression was lost or down regulated in various cancers including liver, breast, lung, brain, stomach, colon and prostate cancers, which suggested that DLC1 may function as a tumor suppressor." (PMID 23988121, 2013). "Further studies reported the downregulation of DLC1 in other human cancers including lung, breast, renal, cutaneous melanomas, nasopharyngeal (NPC), esophageal, cervical, and prostate cancers." (PMID 30278072, 2018).
lung adenocarcinoma (8 papers, 2016 to 2023). A carcinoma that arises from the lung and is characterized by the presence of malignant glandular epithelial cells. "Also, Liu and coworkers revealed that miR-301b-3p promoted lung adenocarcinoma malignancy through suppressing DLC1 expression." (PMID 34488545, 2021). "We therefore analyzed the CPTAC protein dataset for DLC1, Caveolin-1 and PLCD1 expression in lung adenocarcinoma and lung squamous cell carcinoma compared to adjacent normal lung." (PMID 34727930, 2021). "In addition, human lung adenocarcinomas and lung squamous cell carcinomas in the NCI Clinical Proteomic Tumor Analysis Consortium (CPTAC) database displayed a significant inverse correlation (p < 0.0001) between the overall levels of EZH2 and DLC1 protein." (PMID 34862367, 2021).
pancreatic cancer (6 papers, 2011 to 2023). "The aim of the present study was to observe the effect of the DLC-1 gene on pancreatic cancer cell growth and evaluate the feasibility of using the DLC-1 gene in gene therapy for pancreatic cancer." (PMID 24137359, 2013). "Another study which had the aim of determining the role of DLC1 and microRNA-195 in pancreatic cancer, during their research, firstly, they noted that overexpression of miRNA-195 could stop proliferation, migration, and invasion of pancreatic cancer cells." (PMID 32854710, 2020). "The DLC-1 gene may be a promising target in gene therapy for pancreatic cancer." (PMID 24137359, 2013). "The findings suggest that DLC-1 may have an effect on the pathogenesis of pancreatic cancer." (PMID 24137359, 2013). "CDK5 activates tumor-suppressive pathways in pancreatic cancer via EZH2 degradation and in NSCLC by DLC1 activation." (PMID 37993880, 2023).
triple-negative breast carcinoma (5 papers, 2016 to 2025). An invasive breast carcinoma which is negative for expression of estrogen receptor (ER), progesterone receptor (PR), and human epidermal growth factor receptor 2 (HER2). "Furthermore, it has been declared that if reducing EZH2 expression in triple-negative breast cancer cells, DLC1 expression is elevated and curcumin-induced inhibition of cancer growth is facilitated." (PMID 35414117, 2022).
lymphoma (4 papers, 2009 to 2021). A malignant (clonal) proliferation of B- lymphocytes or T- lymphocytes which involves the lymph nodes, bone marrow and/or extranodal sites. "We have observed an increase in invasive thymic cancers, including both thymomas and lymphomas, resulting in significantly shortened life spans in mice heterozygous for the gt Dlc1 allele and an inducible LSL-K-Ras2G12D allele compared with the LSL-K-Ras2G12D only mice." (PMID 22792269, 2012). "Of note, detection of DLC1 methylation in primary lymphoma biopsies and plasma samples from the same patients, showed a concordance of 80%, indicating a possible use of plasma analyses as well." (PMID 25226156, 2014). "This study is a comparative epigenetic evaluation of the methylation status of the DLC1 tumor suppressor gene in naturally-occurring canine lymphoma." (PMID 19912643, 2009). "To better characterize lymphoma in dogs as a model for the human disease, we sequenced the canine DLC1 gene and evaluated the effect of hypermethylation on its expression." (PMID 19912643, 2009). "AP-2 does not appear to contribute significantly to the expression of canine DLC1, as the binding site was uniformly methylated in two of the three lymphoma samples and partially in the normal sample." (PMID 19912643, 2009). "The purpose of this series of experiments was to sequence the canine DLC1 gene and determine whether hypermethylation of the gene is present in canine lymphoma." (PMID 19912643, 2009). "In our results, some of the differentially methylated genes in EHMT2 + MCL cases have also been reported with recurrent genetic alterations in lymphoma, such as ALK, DUSP22, NCOR2, RORA, DLC1, JAG1/2, JAK1, NOTCH4, and CD1938–45." (PMID 34633777, 2021).